SPANXN4 (SPANX family member N4)
Synonyms: SPANX-N4; CT11.9
Tractability: No criterion of Open Targets' tractability assessment is met for any kind of drug.
Gene: Protein-coding gene on chromosome X (143,025,928 to 143,034,702, forward strand). Ensembl gene ENSG00000189326.
Subcellular location (Human Protein Atlas): Plasma membrane; Vesicles; Nuclear membrane
Homologues: Orthologues: macaque SPANXN4 (88% identical). Paralogues in human: SPANXN3 (53% identical), SPANXN2 (49% identical), SPANXN1 (38% identical), SPANXN5 (37% identical).
Diseases named in the same sentence as SPANXN4 in open-access papers:
SPANXN4 is named in the same sentence as 2 diseases in open-access papers, as found by Europe PMC text mining. Sharing a sentence is not in itself a finding about the gene and the disease. The quoted sentences say what the papers report.
COVID-19 (1 paper, 2023). A disease caused by infection with severe acute respiratory syndrome coronavirus 2. "SPANXN4 is essential for spermiogenesis and male fertility, which may predict a potential role for this protein in COVID-19-associated male reproductive tract complications, and warrants further research." (PMID 37520825, 2023). "Analysis of the combined cohorts revealed elevated autoantibody responses against SPANXN4, STK25, ATF4, PRKD2, and CHMP3 proteins in COVID-19 patients." (PMID 37520825, 2023).
cancer (1 paper, 2018). A tumor composed of atypical neoplastic, often pleomorphic cells that invade other tissues. "SPANXN4 belongs to the SPANX multigene family of cancer/testis-specific antigens that play important roles in spermiogenesis." (PMID 29520293, 2018).